PANX3 (pannexin 3)
Description:
Regulator of osteoblast differentiation by functioning as a Ca(2+) channel in the endoplasmic reticulum which regulates calmodulin (CaM) pathways. Allows ATP release into the extracellular space and activation or purinergic receptors.
Synonyms: Px3
Tractability: Small molecule: a structure with a bound ligand is known. Antibody: UniProt places it where antibodies can reach, with medium confidence; UniProt predicts a signal peptide or a membrane-spanning region; its Gene Ontology location is reachable by antibodies, with medium confidence.
Gene: Protein-coding gene on chromosome 11 (124,611,428 to 124,620,356, forward strand). Ensembl gene ENSG00000154143.
Subcellular location: Cell membrane; Cell junction, gap junction; Endoplasmic reticulum membrane
Gene Ontology:
Molecular function: calcium channel activity; gap junction hemi-channel activity; structural molecule activity; wide pore channel activity; channel activity
Biological process: cell-cell signaling; monoatomic cation transport; osteoblast differentiation; calcium ion transmembrane transport; positive regulation of interleukin-1 production; transmembrane transport
Cellular component: endoplasmic reticulum membrane; gap junction; plasma membrane
Genetic constraint (gnomAD): Loss-of-function variants: 19 observed, 33.45 expected, observed/expected ratio (o/e) 0.57, 90% interval 0.4 to 0.83. The upper end of that interval is the gene's LOEUF score, 0.83, which puts it in group 3 of 6, group 1 being the genes least tolerant of losing a copy. Missense variants: 426 observed, 505.4 expected, observed/expected ratio (o/e) 0.84, 90% interval 0.78 to 0.91. Synonymous variants: 194 observed, 212.26 expected, observed/expected ratio (o/e) 0.91, 90% interval 0.81 to 1.03.
Homologues: Orthologues: chimpanzee PANX3 (99% identical), macaque PANX3 (97% identical), rabbit PANX3 (93% identical), pig PANX3 (92% identical), rat Panx3 (92% identical), dog PANX3 (90% identical), guinea pig PANX3 (89% identical), mouse Panx3 (89% identical), tropical clawed frog panx3 (62% identical), zebrafish panx3 (51% identical). Paralogues in human: PANX1 (40% identical), PANX2 (28% identical).
Diseases named in the same sentence as PANX3 in open-access papers:
PANX3 is named in the same sentence as 20 diseases in open-access papers, as found by Europe PMC text mining. Sharing a sentence is not in itself a finding about the gene and the disease. The quoted sentences say what the papers report.
osteoarthritis (7 papers, 2016 to 2025). A noninflammatory degenerative joint disease occurring chiefly in older persons, characterized by degeneration of the articular cartilage, hypertrophy of bone at the margins and changes in the synovial membrane. "Pannexin 3 (Panx3) is a mechanosensitive, channel-forming glycoprotein implicated in the progression of post-traumatic osteoarthritis." (PMID 33499145, 2021). "Cartilage-specific or global deletion of Panx3 protected against development of osteoarthritis induced by destabilization of medial meniscus (DMM) surgery." (PMID 40909173, 2025). "Pannexin 3 (Panx3) is involved in the development and ageing of bone and cartilage as well as in osteoarthritis and intervertebral disc degeneration with protective or detrimental effects depending on the nature of the disease (age-related or injury-induced)." (PMID 36978936, 2023). "However, they also reported that systemic Panx3 deletion led to accelerated progression of aging-induced osteoarthritis in mice." (PMID 40909173, 2025). "Panx3 primarily participates in physiological processes including cartilage/bone development, remodeling, and regeneration, as well as pathological conditions such as obesity, osteoarthritis, and degenerative disc disease." (PMID 40909173, 2025). "Previous work by our group investigating the role of Panx3 in post-traumatic osteoarthritis (OA) demonstrated that both cartilage-specific and whole-body Panx3 knockout (Panx3-/-) mice were resistant to developing OA following destabilization of the medial meniscus." (PMID 33499145, 2021). "The development of Panx3 knockout mice has recently been published and mice lacking the Panx3 gene were shown to be less susceptible to osteoarthritis development." (PMID 27445679, 2016). "Panx3, the third member of Panxs family, is involved in the regulation of dynamic biological functions and plays a critical role in pathogenesis of many diseases 22, such as saturated fatty acid‐induced inflammation 16, osteoarthritis 23 and dentin hypersensitivity." (PMID 27679980, 2017).
osteosarcoma (6 papers, 2016 to 2025). A usually aggressive malignant bone-forming mesenchymal neoplasm, predominantly affecting adolescents and young adults. "Particularly, PANX3, implicated in osteoblast differentiation and osteosarcoma, is dysregulated in carcinogenesis, showing upregulation in axillary sweat gland carcinoma and osteosarcoma, correlating with osteosarcoma prognosis." (PMID 40075313, 2025). "A previous study also confirmed that overexpression of PANX3 significantly promoted the proliferation, invasion for osteosarcoma cells and attenuated the antitumor efficacy of mir-431-5p mimics in osteosarcoma cells." (PMID 40075313, 2025). "Highly expressed Panx3 inhibited apoptosis and promoted the proliferation, migration and invasion of osteosarcoma cells." (PMID 40909173, 2025). "The five biomarkers (CD36, CLDN11, EPYC, PANX3, and STOM) were screened to construct an AAMRGs risk model with prognostic value, providing a new reference for the prognosis and treatment of osteosarcoma." (PMID 40075313, 2025). "Validation of gene expression through public databases and RT-qPCR results showed significant upregulation of EPYC and PANX3 in osteosarcoma samples, while CD36, CLDN11, and STOM were significantly downregulated." (PMID 40075313, 2025). "Pannexin 3 is a member of the pannexin family of proteins and observed to be highly expressed in osteosarcoma compared to normal sample." (PMID 38966281, 2024). "Panx3 was highly expressed in osteosarcoma and exerted pro-cancer function." (PMID 40909173, 2025). "Recent research indicates a significant correlation between PANX3 and osteosarcoma." (PMID 40075313, 2025). "Targeting PANX3, for example, can inhibit the tumorigenesis of osteosarcoma." (PMID 37894336, 2023). "Notably, three transcriptional modules out of the top ten MRs, CDK6, EGFR and PANX3, have already been proven to be critical mediators of pathogenesis in osteosarcoma." (PMID 37894336, 2023). "Panx3 plays a role in proliferation and differentiation of cells in skin, cartilage and bone, so we predict that we will soon learn more about a potential role for Panx3 in skin cancer and osteosarcomas." (PMID 27229305, 2016). "The differential analysis showed that in the osteosarcoma group, the expression of EPYC and PANX3 was obviously elevated, whereas the expression of CD36, CLDN11 and STOM was markedly decreased." (PMID 40075313, 2025). "IFITM5, MMP13, PANX3, and MAGEA6 were some of the most overexpressed genes in osteosarcoma samples, while SLC4A1, HBA1, HBB, AQP7 genes were some of the top downregulated genes." (PMID 38966281, 2024). "In order to develop a risk model with the optimal prognostic predictive capacity of these DE-AAMRGs in osteosarcoma patients, we performed univariate Cox analysis and utilized the LASSO method to select a panel of five biomarkers (CD36, CLDN11, EPYC, PANX3, and STOM)." (PMID 40075313, 2025). "The roles of PANX3 and CD36 are well established; however, the specific functions of EPYC, CLDN11, and STOM in osteosarcoma remain unclear." (PMID 40075313, 2025). "The IHC analysis displayed that osteosarcoma tissues express significantly higher levels of EPYC and PANX3 compared to adjacent non-tumorous tissues." (PMID 40075313, 2025).
papilloma (3 papers, 2016 to 2025). A benign epithelial neoplasm that projects above the surrounding epithelial surface and consists of villous or arborescent outgrowths of fibrovascular stroma. "Panx3 transcripts were reduced, and Panx3 systemic knockout mice could be more susceptible to precancerous papillomas." (PMID 40909173, 2025). "The positive association between tumor risk and Panx3 levels in normal skin, but reduced Panx3 expression in papillomas and carcinomas, supports the interpretation that the primary role of Panx3 during tumor development is in influencing tumor susceptibility rather than tumor maintenance." (PMID 27506198, 2016). "Unfortunately, one WT mouse (which developed a papilloma and was included in any analyses of papilloma incidence) died during the treatment period before reaching end‐point of causes independent of the study and was therefore removed from all papilloma volume analyses (WT N = 4, Panx3 KO N = 5)." (PMID 39560179, 2025). "When analysed at end‐point (week 28), the average papilloma volume was found to be significantly increased in Panx3 KO mice compared to WT mice (P = 0.0491)." (PMID 39560179, 2025). "On the contrary, PANX3 plays a tumour‐suppressive role where it reduces the incidence and growth of precancerous papillomas." (PMID 39560179, 2025). "Panx3 transcript levels were markedly reduced in papillomas and carcinomas compared to untreated tail skin." (PMID 39560179, 2025). "Taken together, this illustrates Panx3 KO mice tend to have increased papilloma incidence, volumes and growth over time when subjected to a cutaneous carcinogenesis protocol." (PMID 39560179, 2025). "Generally, Panx3 KO mice exhibited a papilloma incidence twice that of WT mice, with KO mice developing an average of 2.2 papillomas per mouse compared to the average of 1 papilloma per WT control." (PMID 39560179, 2025). "Using a previously generated cohort of mouse tail skin, benign papillomas, and malignant carcinomas, we assessed the expression levels of Panx3." (PMID 27506198, 2016). "Panx3 expression in pre-treatment tail skin was positively correlated with papilloma burden (p = 0.032, rho = 0.28), as well as with carcinoma risk in males (p = 0.012), indicating that elevated Panx3 levels are associated with both early and late stages of tumor development." (PMID 27506198, 2016). "However, because our assessment of the effects of PANX3 on cSCC formation was performed using a global Panx3 KO mouse model, it remains to be seen whether the reduced papilloma incidence and growth with Panx3 ablation were due to reductions in PANX3 activity, signalling and/or protein interactions." (PMID 39560179, 2025). "Of the mice in the pilot study, three of five WT and all five Panx3 KO mice developed papillomas, but none developed carcinomas." (PMID 39560179, 2025). "Conversely, global Panx3 (knockout) KO mice subjected to the 7,12‐dimethylbenz(a)anthracene/12‐otetradecanoylphorbol‐13‐acetate (DMBA/TPA) cutaneous carcinogenesis model have increased papilloma growth and incidence." (PMID 39560179, 2025). "To assess PANX3 function in cutaneous carcinogenesis, we employed the 7,12‐dimethylbenz(a)anthracene/12‐otetradecanoylphorbol‐13‐acetate (DMBA/TPA) model using our global Panx3 knockout (KO) mice, where 60% of wild‐type and 100% of KO mice formed precancerous papillomas." (PMID 39560179, 2025). "For PANX3, trends seen in cSCC corresponded to those observed in DMBA/TPA‐induced murine papillomas and carcinomas, previous immunofluorescence microscopy findings from our group and HNSCC in silico findings, where Panx3/PANX3 levels were reduced in each case compared to controls." (PMID 39560179, 2025).
diabetes (2 papers, 2016 to 2023). "Finally, in humans the genomic region containing PANX3 has been previously associated with the development of obesity, as well as diabetes and serum adiponectin concentrations." (PMID 27506198, 2016).
skin cancer (2 papers, 2016). "While the details of interactions between Panx1, Panx3, and inflammation in skin remain to be elucidated, these data provide support for the proposal that alterations in Panx3 levels and/or signaling contribute to skin tumor susceptibility through effects on acute inflammatory responses." (PMID 27506198, 2016).
cutaneous squamous cell carcinoma (1 paper, 2025). "PANX1 and PANX3 function in skin homeostasis and keratinocyte differentiation but were previously reduced in a small cohort of human cutaneous squamous cell carcinoma (cSCC) tumours compared to normal epidermis." (PMID 39560179, 2025). "Abstract figure legend PANX1 and PANX3 show opposite expression patterns in patient‐derived normal skin and cutaneous squamous cell carcinoma (cSCC) tumours, with PANX1 increased and PANX3 mRNA decreased in cSCC tumours compared to skin." (PMID 39560179, 2025).
dermatitis (1 paper, 2025). An inflammatory process affecting the skin. "Additionally, ablating Panx3 in mice was found to increase inflammatory signalling in the neonatal epidermis and the incidence of dermatitis in an aged cohort." (PMID 39560179, 2025).
Hypertension (1 paper, 2026). The presence of chronic increased pressure in the systemic arterial system. "Additionally, Panx3 deletion specifically in endothelial cells induces hypertension in mice, highlighting a vascular role." (PMID 41569301, 2026).
joint diseases (1 paper, 2021). "In vivo, genetic deletion of Panx3 in mice leads to abnormal differentiation of hypertrophic chondrocytes; Lac of Panx3 plays a role in joint diseases and a delay in osteoblast differentiation and mineralization." (PMID 34392490, 2021).
malnutrition (1 paper, 2021). Inadequate nutrition resulting from poor diet, malabsorption, or abnormal nutrient distribution. "Further examination revealed Panx3−/− mice showed no obvious difference in the first hair cycle and no premature hair follicle anagen cessation, hair loss, or hair thinning commonly associated with severe malnutrition (P4 and P10)." (PMID 33469169, 2021).
metabolic syndrome (1 paper, 2016). A cluster of metabolic risk factors for CARDIOVASCULAR DISEASES and TYPE 2 DIABETES MELLITUS. "Additional observations have implicated Panx3 in the persistent disseminated inflammation and metabolic syndrome associated with obesity." (PMID 27506198, 2016).
pulpitis (1 paper, 2017). Inflammation of the dental pulp. "The immunosuppressive role of Panx3 may be used for therapeutic prevention of dental pulp inflammation." (PMID 27679980, 2017). "Moreover, Western blot, dual‐luciferase reporter assay, immunofluorescence staining, qRT‐PCR and ELISA results showed that Panx3 participated in dental pulp inflammation in a NF‐κB‐dependent manner." (PMID 27679980, 2017). "However, the effect of Panx3 in defined cell populations on pulpitis remains unascertained." (PMID 27679980, 2017). "Taken together, Panx3 was firstly proved to be a negative regulator of TNF‐α‐mediated inflammatory response and may be a therapeutic target of dental pulp inflammation." (PMID 27679980, 2017).
tumor (6 papers, 2010 to 2025). "Pre-treatment Panx3 gene expression levels in normal skin are associated with tumor susceptibility and inhibition of Panx function strongly influences inflammation." (PMID 27506198, 2016). "Further analysis of these regions identified Pannexin 3 (Panx3) as a strong candidate gene for the BMI/tumor susceptibility locus on chromosome 9." (PMID 27506198, 2016). "In order to evaluate the relationship between Panx3 and tumorigenesis, we assessed whether pre-treatment levels of Panx3 were associated with tumor development or progression." (PMID 27506198, 2016). "Additionally, Panx3 may serve as a useful biomarker for certain tumor types, while Panx1 mutations have been linked to metastatic breast cancer." (PMID 40227837, 2025). "To explore PANX1 and PANX3 transcript expression in patient‐derived cSCC tumours compared to normal skin controls, we first performed a bioinformatics search by investigating two cSCC RNA‐seq studies available on the GEO database." (PMID 39560179, 2025). "In our patient sample cohort, we found that PANX1 protein is upregulated whereas PANX3 mRNA is downregulated in human cSCC tumour fragments compared to patient‐matched normal skin." (PMID 39560179, 2025). "In human cSCC patient‐derived tumours and aged epidermis, immunofluorescence microscopy analysis using a small cohort of samples indicated that both PANX1 and PANX3 were visibly reduced in cSCC tumours." (PMID 39560179, 2025). "Panx1 drives tumor progression through ubiquitous overexpression that accelerates malignant proliferation and invasion, whereas Panx3 exerts tumor-suppressive effects." (PMID 40909173, 2025). "In cutaneous squamous cell carcinoma (cSCC), Panx1 and Panx3 exhibit divergent tumor-modulatory roles." (PMID 40909173, 2025). "Overall, this indicates that PANX3 transcripts are decreased in human cSCC tumours compared to patient‐matched unaffected epidermis and dermis." (PMID 39560179, 2025). "MicroRNA-431-5p could target and regulate the expression of Panx3, exerting tumor suppressor function." (PMID 40909173, 2025). "Collectively, these findings suggest PANX1 and PANX3 dysregulation may have potential tumour‐promoting and tumour‐suppressive effects for keratinocyte transformation, respectively." (PMID 39560179, 2025). "Taken together, this indicates that in cSCC, PANX1 may exhibit pro‐tumour activities and PANX3 may exhibit anti‐tumour activities." (PMID 39560179, 2025). "Panx3 expression is also associated with tumor development and we demonstrate that inhibition of Pannexin function causes alterations in TPA-induced inflammatory signaling, providing a plausible mechanism for the relationship between Panx3 and tumorigenesis." (PMID 27506198, 2016). "In the skin pre-treatment Panx3 expression levels are correlated with both BMI and tumor burden." (PMID 27506198, 2016). "Notably, both studies contained small N values, and control tissues consisted of either paired human skin organoids or unpaired healthy skin, making it difficult to draw substantial conclusions about PANX1 and PANX3 expression in this cohort of patient‐derived cSCC tumours." (PMID 39560179, 2025). "Beginning with PANX3 we determined that in human full‐thickness skin samples, PANX3 was highly abundant, and PANX3 transcripts were significantly reduced (P = 0.0452) in cSCC tumour fragments compared to patient‐matched skin samples containing the epidermal and dermal layers." (PMID 39560179, 2025). "Also chosen for validation was pannexin 3, a gap junction protein with tumor suppressive capacity." (PMID 21085651, 2010). "Despite the larger N values of this study, PANX1 and PANX3 mRNA were detectable only in 31 normal tissue and 89 HNSCC tumour samples." (PMID 39560179, 2025).
cancer (4 papers, 2016 to 2025). A tumor composed of atypical neoplastic, often pleomorphic cells that invade other tissues. "In this work we have also identified a potential role for Panx3, a member of the recently described Pannexin gene family, in both BMI and cancer susceptibility." (PMID 27506198, 2016). "This study concurs with previous research by finding significant overexpression of PANX3 in cancer samples." (PMID 40075313, 2025). "For the chemical carcinoma model, we used our previously established Panx3 KO mouse model to assess the potential role of PANX3 in cSCC carcinogenesis because currently there are no commercially available PANX3‐specific channel blockers." (PMID 39560179, 2025). "Congruent with human data, Panx3 expression was markedly reduced in tumors, with carcinomas showing no significant expression of Panx3 (p < 1e-10)." (PMID 27506198, 2016).
cardiovascular disease (1 paper, 2026). "As such, future research into pannexin function in cardiovascular disease should not entirely rule out Panx2 and Panx3." (PMID 41569301, 2026).
PANX3 also shares sentences with these, for which no sentence is quoted: intervertebral disc degeneration (1 paper); liver disease (1); Obesity (1); periodontal disease (1); sweat gland carcinoma (1).